SIRT6 (sirtuin 6)
Diseases named in the same sentence as SIRT6 in open-access papers (continued):
Sharing a sentence is not in itself a finding about the gene and the disease.
gastric cancer (continued). "Moreover, immune-related studies highlight reduced SIRT6 expression in dysfunctional NK cells in gastric cancer, implicating it in impaired antitumor immunity." (PMID 41463311, 2025). "Additionally, Sirt1 downregulation and Sirt6 upregulation were detected in the presence of MDM2 in gastric cancer cells." (PMID 38254877, 2024). "The ROS scavenger NAC significantly reduced Sirt6-mediated gastric cancer cell apoptosis." (PMID 38254877, 2024). "The knockdown of Sirt6 via shSirt6 treatment decreased gastric cancer cell death." (PMID 38254877, 2024). "Sirt6 expression was significantly lower in gastric cancer tissues than in normal tissues." (PMID 38254877, 2024). "Knockdown of SIRT6 promotes ferroptosis in gastric cancer cells." (PMID 35847022, 2022). "For example, SIRT6 inhibits the JAK2/STAT3 pathway to suppress the growth of gastric cancer." (PMID 33510943, 2021). "However, there were also controversial reports that SIRT6 inhibits the proliferation of pancreatic and gastric cancer cells." (PMID 30524965, 2018). "SIRT6 levels of serum from gastric cancer patients (n = 22, 65.27 ± 12.50 years old, 40.9% females) and healthy controls (n = 22, 63.50 ± 10.77 years old, 45.4% females) were measured to evaluate the correlation between circulating SIRT6 levels and cancer cachexia development." (PMID 39971710, 2025). "SIRT6 plays a multifaceted role in gastric cancer (GC), exerting both tumor-suppressive and context-dependent oncogenic functions." (PMID 41463311, 2025). "SIRT6 overexpression suppresses SIRT1, leading to elevated MDM2 and ROS levels that drive gastric cancer cell death and reduce xenograft tumor growth." (PMID 41463311, 2025). "In summary, we found that elevated Sirt6 expression leads to Sirt1 suppression via MDM2, inducing gastric cancer cell death." (PMID 38254877, 2024). "We showed that Sirt6 upregulates MDM2, which suppresses Sirt1 expression and induces ROS production, thereby promoting gastric cancer cell death." (PMID 38254877, 2024). "Another study showed that silencing SIRT6 induced ferroptosis in gastric cancer cells by inducing inactivation of Keap1-Nrf2 and low expression of GPX4, thereby improving the sensitivity of gastric cancer cells to sorafenib." (PMID 36038533, 2022). "The activity of the three proteins, Sirt6, MDM2, and Sirt1, results in increased ROS production, which is responsible for an anti-tumorigenic effect, suggesting that these three molecules are potential targets for the treatment of gastric cancer." (PMID 38254877, 2024). "Sirt6 overexpression in gastric cancer cells was predominantly detected in the nucleus and not in the cytoplasm, as indicated by Western blot and immunofluorescence analyses." (PMID 38254877, 2024). "The inhibition of Sirtuins 6 (SIRT6), a member of the Sirtuin family of NAD (+)-dependent enzymes, lead to the inactivation of the Keap1/Nrf2 signalling pathway and downregulation of GPX4, which overcomes sorafenib resistance by promoting ferroptosis in gastric cancer." (PMID 36105219, 2022).
glioma (19 papers, 2015 to 2025). A benign or malignant brain and spinal cord tumor that arises from glial cells (astrocytes, oligodendrocytes, ependymal cells). "Increasing SIRT6 levels in glioma cells, specifically the U87-MG and T98G cell lines, significantly reduces cell growth, decreases cell viability, and increases cell injury." (PMID 40710366, 2025). "Mechanistic studies revealed that the effect of BLA on inducing apoptosis and inhibiting the proliferation of glioma cells was blocked by SIRT6 knockout." (PMID 39845013, 2025). "Mechanistic studies revealed that BLA regulates glioma cell proliferation and apoptosis by increasing the expression of SIRT6 and then inhibiting H3K9 and H3K56 acetylation." (PMID 39845013, 2025). "In summary, our study indicated that BLA is a potential therapeutic agent for glioma that targets SIRT6 to inhibit glioma cell proliferation and induce apoptosis." (PMID 39845013, 2025). "Restoring SIRT6 in glioma cells leads to increased levels of reactive oxygen species and lactate dehydrogenase, enhancing the sensitivity of glioma cells to oxidative stress-induced apoptosis." (PMID 40710366, 2025). "SIRT6 expression is underexpressed in glioma tissues compared with normal tissues, and there is an inverse correlation between miR-33a and SIRT6 levels." (PMID 40710366, 2025). "Overall, SIRT6 inhibits glioma cell proliferation, migration, and invasion through the negative regulation of NOTCH3." (PMID 40710366, 2025). "Conversely, knocking down SIRT6 increases cell proliferation, migration, and invasion in the same glioma cell lines, further supporting its function as a tumor suppressor." (PMID 40710366, 2025). "Nuclear-localized SIRT6 is notably downregulated in glioma and acts as a tumor suppressor through various mechanisms, including inhibition of the JAK2/STAT3 and NOTCH3 signaling pathways." (PMID 40710366, 2025). "Further, recent studies have shown that SIRT6 is generally considered to have a suppressive role in gliomas." (PMID 39845013, 2025). "A similar effect was observed also in glioma cells in which SIRT6 suppresses the expression of poly(C)-binding protein 2 (PCBP2) through H3K9 deacetylation at its promoter, hence blocking tumor cell growth." (PMID 33800266, 2021). "SIRT6 protein expression is reduced in glioma cell lines, where it negatively correlates with the expression of miR-33a." (PMID 33800266, 2021). "Whereas in glioma cells, SIRT6 was reported to increase ROS, thus reduced cell survival under H2O2 treatment." (PMID 33436551, 2021). "Functional MST1 overexpression has been marked by the induction of SIRT6 (Sirtuin 6), reducing glioma cell viability and colony formation and promoting apoptosis through the activation of FOXO3a transcription factor." (PMID 33477668, 2021). "SIRT6 overexpression also repressed glioma cell growth while SIRT6 knockdown contributes to its growth." (PMID 31591350, 2019). "Mechanistically, miR-33a targets SIRT6 and promotes tumor development in human glioma by regulating its expression." (PMID 31119097, 2019). "Considering the differences, targeting SIRT6 may be considered a novel strategy for treating gliomas." (PMID 39845013, 2025). "Furthermore, SIRT6 overexpression lowers oxidative stress levels in glioma cells by reducing reactive oxygen species and malondialdehyde levels and increasing antioxidant enzyme activity." (PMID 40710366, 2025). "Overexpression of SIRT6 in glioma cell lines (U87 and U251) decreases cell proliferation, migration, and invasion, indicating its role in suppressing the aggressive characteristics of glioma cells." (PMID 40710366, 2025). "Experimental studies in glioma models revealed that SIRT6 overexpression suppresses tumor growth by promoting histone deacetylation and cell-cycle arrest, whereas SIRT1 limits androgen biosynthesis through FOXO1 deacetylation, thereby restraining tumor progression." (PMID 41425553, 2025).
glioma (continued). "In glioma cells, SIRT6 is a direct target of miR-33a; when miR-33a is overexpressed, SIRT6 levels decrease at both the mRNA and protein levels, indicating that miR-33a negatively regulates SIRT6." (PMID 40710366, 2025). "In subsequent experiments, we further demonstrated that the effect of BLA on glioma cell proliferation and apoptosis was greatly blocked by the downregulation of SIRT6 expression, indicating that SIRT6 is required for the antitumor effects of BLA on U87MG cells." (PMID 39845013, 2025). "The current study confirms the carcinogenic effects of SIRT6 in glioma." (PMID 36568393, 2022). "In addition, overexpression of miR-33a was observed in clinical glioma specimens and cell lines, which negatively regulated the expression of SIRT6 by targeting its mRNA 3’UTR." (PMID 35006436, 2020). "Conversely, SIRT6 expression wasmoderately and significantly increased in all gliomas." (PMID 25791281, 2015). "Dysregulation of the miR-33a/SIRT6 pathway contributes to glioma progression by promoting tumor growth and resistance to apoptosis; thus, targeting this pathway could provide new therapeutic strategies for treating glioma." (PMID 40710366, 2025). "In addition, overexpression of miR-33a was observed in clinical glioma specimens and cell lines, which negatively regulated the expression of SIRT6 via targeting the 3’UTR mRNA, thereby decreasing ROS production and increasing Bcl-2 expression to inhibit apoptosis." (PMID 35006436, 2020). "Furthermore, in human glioma cells, evidence shows that SIRT6 acts as tumor suppressor." (PMID 31591350, 2019). "Collectively, these results indicate that BLA induces the expression of SIRT6 to modulate the acetylation levels of H3K9 and H3K56, and subsequently regulates glioma cell proliferation and apoptosis." (PMID 39845013, 2025). "There is evidence that SIRT6 is regulated by MST1 and miR-33a and can inhibit the activity of glioma cells." (PMID 36568393, 2022). "SIRT6 is downregulated in human glioma tissues and deacetylates H3K9ac on the promoter of PCBP2 to downregulate PCBP2 expression and inhibit glioma cell growth." (PMID 35463332, 2022). "Importantly, SIRT6 overexpression inhibits the activation of the JAK2/STAT3 (Janus kinase 2/signal transducer and activator of transcription 3) signaling pathway, which is often overactive in gliomas, contributing to the anti-cancer effects of SIRT6." (PMID 40710366, 2025).
non-small cell lung carcinoma (18 papers, 2016 to 2025). A group of at least three distinct histological types of lung cancer, including non-small cell squamous cell carcinoma, adenocarcinoma, and large cell carcinoma. "SIRT6 was found to be overexpressed in skin cancer and non-small cell lung cancer (NSCLC), osteosarcoma, colon carcinoma, serous ovarian cancer, and clear cell renal cell carcinomas (ccRCC), showing a poor prognostic value." (PMID 34639169, 2021). "In non-small cell lung cancer, SIRT6 induced epithelial-to-mesenchymal transition by regulating the snail/KLF4 pathway." (PMID 33198792, 2020). "Supportively, knock-down of SIRT6 sensitized non-small cell lung cancer cells to paclitaxel treatment, and inhibition of SIRT6 sensitized lymphoma cells to doxorubicin." (PMID 33198792, 2020). "Here, we report that elevated SIRT6 expression was correlated with clinicopathological parameters such as T and N classification in non-small cell lung cancer (NSCLC) patient tumors." (PMID 27777384, 2016). "Research shows that inhibition of Raf-MEK-ERK pathway by Cyclic AMP signaling can promote ubiquitin-proteasomal degradation to reduce SIRT6 expression in non-small cell lung cancer cells." (PMID 26967560, 2016). "The SIRT6 may promote the growth of erlotinib-resistant non-small cell lung cancer cells by activating the HIF-1α/HK2 signaling axis to promote aerobic glycolysis in tumor cells." (PMID 39876842, 2024). "Overexpression of SIRT6 is found in skin cancer and in non-small cell lung cancer (NSCLC) with poor prognostic value, but in other types of cancers, it may be considered a tumor suppressor." (PMID 33440786, 2021). "In H1299 non-small cell lung carcinoma cells, treatment of UBSC039 decreased acetylation of histone H3 K9 and K56, two known SIRT6 deacetylation targets." (PMID 34650436, 2021). "In non-small cell lung cancer (NSCLC), the inhibition of proliferation mediated by SIRT6 is the result of the suppression of Twist1 expression, a key player involved in two different tumor processes such as metastatization and epithelial-mesenchymal transition (EMT)." (PMID 33800266, 2021).
Alzheimer disease (17 papers, 2014 to 2025). A progressive, neurodegenerative disease characterized by loss of function and death of nerve cells in several areas of the brain leading to loss of cognitive function such as memory and language. "In humans, Sirt6 has a pivotal role during brain aging, and its loss of function is correlated with the appearance of neurodegenerative diseases such as Alzheimer’s disease." (PMID 34720996, 2021). "Our study suggests that the decay of SIRT6 levels during aging and in Alzheimer’s disease could be a key mechanism causing the deterioration of mitochondrial functions." (PMID 36653345, 2023). "Sirtuins contains of SIRT1, SIRT3, and SIRT6 in saliva can be an extra technique for non-invasive intravital diagnosis of Alzheimer’s disease in elderly individuals." (PMID 39484071, 2024). "The activation of apoptosis by inducing the expression of SIRT6 and inhibiting the mTOR pathway by 3‐iodothyronamine was found in a transgenic model of Alzheimer's disease." (PMID 37381696, 2023). "SIRT6 is an emerging risk factor of AD with 12 articles listed in PubMed under “SIRT6” AND “Alzheimer’s disease” (January 22, 2020)." (PMID 32121304, 2020). "More recently, SIRT6 has also been shown to have implications in brain aging and major neurodegenerative diseases such as Alzheimer’s disease (AD)." (PMID 29966233, 2018). "Targeting the acetylation of Tau at residue 174 or restoring SIRT6 levels could mitigate Tau accumulation and potentially offer therapeutic strategies for Alzheimer’s disease." (PMID 38087392, 2023). "In Alzheimer’s disease, genomic instability has been reported, and SIRT6’s role in this context may have implications for disease progression." (PMID 38087392, 2023). "Similarly, an obvious downregulation of SIRT6 was observed in hippocampus and saliva of patients with Alzheimer disease, which is also a disease in close relation to oxidative stress." (PMID 34149393, 2021). "Also, in patients with Alzheimer’s disease, lower expression of SIRT6 was measured, which hints the neuroprotective role of SIRT6." (PMID 34650436, 2021). "Moreover, natural products emerged as SIRT6 modulators can be successfully applied to treat cancer, inflammation, Alzheimer’s Disease, etc." (PMID 34746014, 2021). "Furthermore, SIRT6 is also known to alter adult hippocampal neurogenesis through its influence on the number of glial and neuronal cells, thereby, offering a therapeutic arc in Alzheimer’s disease." (PMID 33920726, 2021). "Investigating an Alzheimer's disease (AD) mouse model [transgenic for five familial AD (5XFAD) mutations associated with the Amyloid precursor protein (APP) and Presenilin 1], as well as brain samples from AD patients, Jung and colleagues reported a reduction in SIRT6 protein in these models." (PMID 28642687, 2017). "Alzheimer’s disease patients showed decreased expression of SIRT6 and mice lacking SIRT6 showed TAU protein stabilization and increased phosphorylation, via the activation of the glycogen synthase kinase 3 (GSK3)." (PMID 36816109, 2023).
Hyperglycemia (17 papers, 2017 to 2024). An increased concentration of glucose in the blood. "Because Sirt6 down-regulation by statins was shown to be a cause of hyperglycemia, we further investigated whether Sirt6 activation by chemical activators, specifically MDL801 and fucoidan, could prevent this." (PMID 33052223, 2020). "Hyperglycemia appeared to promote the mRNA expression of SIRT6 and TETs, which in turn might cause the dynamic changes of 5mC and 5hmC in WBCs from T2DM patients." (PMID 30987683, 2019). "Sirt6 overexpression protected model mice from developing hyperglycemia and decreased glucose tolerance after eating a high-fat diet (HFD)." (PMID 36465178, 2022). "Our results therefore indicate that recovering the expression and deacetylase activity of Sirt6 inhibits statin-mediated hepatic gluconeogenesis and hyperglycemia." (PMID 33052223, 2020). "Sirt6 overexpression was also able to prevent hyperglycemia induced by atorvastatin or rosuvastatin in mice." (PMID 33052223, 2020). "We also found that other renal parenchymal cells including rat glomerular mesangial cells, rat glomerular endothelial cells, and human tubule epithelial cells (HK-2) had different expression patterns of Sirt6 in response to hyperglycemia or ADR." (PMID 28871079, 2017). "In DR, the HDAC Sirt6 serves as an environmental sensor of hyperglycemia, and its downregulation results in increased VEGF expression, which may represent an early step in proliferative DR pathogenesis." (PMID 36833344, 2023). "Because SIRT6 can lower blood glucose levels by enhancing glycolysis and glucose uptake, SIRT6 inhibition has been considered a promising therapeutic treatment for hyperglycemia." (PMID 36465178, 2022). "Thus, Sirt6 may represent an epigenetic environmental integrator in DR—downregulated Sirt6 expression in response to hyperglycemia leads to decreased H3K56 deacetylation and upregulation of VEGF production in Müller glia." (PMID 36833344, 2023). "SIRT-6 induction of activated protein kinase (AMPK) signaling, through H3K9 and H3K56, contributed to hyperglycemia-induced mitochondrial dysfunction and apoptosis in podocytes." (PMID 36983082, 2023). "Thus, Sirt6 activation may offer a promising strategy for preventing statin-induced hyperglycemia." (PMID 33052223, 2020). "Moreover, the Sirt6 activator MDL801 prevented gluconeogenesis and hyperglycemia induced by statin in mice." (PMID 33052223, 2020).